METTL3 (methyltransferase 3, N6-adenosine-methyltransferase complex catalytic subunit)
Diseases named in the same sentence as METTL3 in open-access papers (continued):
Sharing a sentence is not in itself a finding about the gene and the disease.
atherosclerosis (25 papers, 2021 to 2025). A disease characterized by the build-up of fatty material and calcium deposition in the arterial wall resulting in partial or complete occlusion of the arterial lumen. "METTL3 is one of the major m6A modified proteins most commonly reported to be associated with the development of atherosclerosis." (PMID 39227813, 2024). "Previous studies have shown that METTL3-mediated methylation is involved in the inflammatory cascade response in endothelial cells (ECs) and is closely associated with hemodynamics and the pathogenesis of atherosclerosis." (PMID 40662138, 2025). "This further supports the regulatory role of METTL3 in inflammatory-related genes and its potential as a therapeutic target for atherosclerosis." (PMID 40225569, 2025). "Considering the pivotal role of macrophage-mediated inflammatory responses in atherosclerosis, we assessed the expression levels of METTL3 in ox-LDL-induced macrophages." (PMID 40225569, 2025). "The experimental results demonstrated the roles of ALKBH5, WTAP and METTL3 in atherosclerotic processes, which are consistent with recent studies on m6A in atherosclerosis." (PMID 40225569, 2025). "METTL3 is up-regulated during the proliferation and migration of human coronary smooth muscle cells (HCASMCs) and is involved in the pathogenesis of atherosclerosis by affecting protein synthesis and energy metabolism." (PMID 40662138, 2025). "During atherosclerosis, METTL3 regulates hepatoma-derived growth factor (HDGF) mRNA stability in macrophages through m6A modification, increasing HDGF expression that, in turn, accelerates glycolysis and enhances mitochondrial dysfunction." (PMID 40066451, 2025). "In vitro experiments were conducted to further investigate the effects of ALKBH5, WTAP and METTL3 on atherosclerosis." (PMID 40225569, 2025). "METTL3 knockdown prevents the progression of atherosclerosis by inhibiting the JAK2/STAT3 pathway via IGF2BP1." (PMID 40005339, 2025). "In VSMCs, METTL3-mediated m6A modification impacts the expression of genes related to cell proliferation and migration, which are key processes in atherosclerosis and restenosis development." (PMID 39834386, 2024). "Compared with the atherosclerosis+si‐METTL3+vector group, the ratio of plaque to the vascular area in the aortas of mice in the atherosclerosis+si‐METTL3+H19 group was significantly increased (p < .05)." (PMID 39432244, 2024). "H19 was the primary target lncRNA molecule of METTL3‐mediated m6A modification in the pathogenesis of atherosclerosis." (PMID 39432244, 2024). "In the aortas of atherosclerosis mice, overall m6A levels were significantly elevated compared with controls (p < .05), with METTL3 and METTL14 mRNA and protein levels notably increased (p < .05)." (PMID 39432244, 2024). "In summary, H19 is the main target lncRNA molecule of METTL3 mediated‐m6A modification in the pathological process of atherosclerosis." (PMID 39432244, 2024). "In the vivo atherosclerosis model, repeated administration of METTL3 shRNA prevented the atherogenic process and the upregulation of NLRP3." (PMID 39227813, 2024). "Upregulation of METTL3 can significantly increase the expression of hsa_circ_0029589, and promote macrophage pyroptosis and inflammatory response in atherosclerosis." (PMID 39227813, 2024). "Overexpression of H19 reversed these effects, indicating METTL3's role in promoting atherosclerosis by stabilizing H19 through m6A modification." (PMID 39432244, 2024). "Collectively, this study has revealed the little‐known mechanism of m6A participating in atherosclerosis by regulating lncRNA expression and demonstrated that targeted inhibition of METTL3 and H19 is a potential treatment strategy for atherosclerosis." (PMID 39432244, 2024). "A notable increase in serum IL‐1β, IL‐18, and IL‐6 levels was observed in atherosclerosis mice, and METTL3 knockdown in atherosclerosis mice significantly decreased these inflammatory markers." (PMID 39432244, 2024).
atherosclerosis (continued). "METTL3‐mediated m6A modification regulated H19 expression, thereby aggravating atherosclerosis by activating pyroptosis." (PMID 39432244, 2024). "We then explored the effects and potential mechanisms of METTL3‐mediated m6A modification in promoting atherosclerosis progression through both in vivo and in vitro experiments." (PMID 39432244, 2024). "The latest studies have elucidated that IRF-1 inhibits the expression of hsa_circ_0029589 by inducing m6A levels and METTL3 expression, thereby promoting macrophages pyroptosis and inflammatory response in atherosclerosis." (PMID 39227813, 2024). "Compared with the atherosclerosis+siNC+vector group, the ratio of plaque to the vascular area in the aortas of mice in the atherosclerosis+si‐METTL3+vector group was markedly decreased (p < .05)." (PMID 39432244, 2024). "Subsequent in vivo experiments demonstrated that reducing METTL3 expression effectively mitigated atherosclerosis progression in mice, while H19 upregulation exacerbated the condition." (PMID 39432244, 2024). "Our findings showed that METTL3 knockdown significantly inhibited HAEC pyroptosis, illustrating in reverse that METTL3‐mediated m6A modification is a key aggravating factor of atherosclerosis." (PMID 39432244, 2024). "Compared with the atherosclerosis+siNC+vector group, serum TC, TG, and LDL‐C levels in mice in the atherosclerosis+si‐METTL3+vector group significantly decreased (p < .05), while the HDL‐C level markedly increased." (PMID 39432244, 2024). "Briefly, H19 overexpression significantly aggravated atherosclerosis alleviated by METTL3 knockdown." (PMID 39432244, 2024). "Plaques of varying degrees were observed in the aortas of mice in the atherosclerosis, atherosclerosis+siNC+vector, atherosclerosis+si‐METTL3+vector, and atherosclerosis+si‐METTL3+H19 groups, and they were distributed across various sites." (PMID 39432244, 2024). "Our results describe the role of m6A and METTL3 in atherogenic progression and identify therapeutic strategies against atherosclerosis through m6A modification and its related targets." (PMID 35001873, 2022). "The objectives of this study were to investigate differentially expressed m6A methylated peaks and mRNAs, along with the regulatory role of methyltransferase 3 (METTL3) in pathological processes of atherosclerosis." (PMID 36230944, 2022). "To further detect the proatherogenic role of endothelial METTL3, we carried out a standard atherosclerosis study in Apoe-/- EC-Mettl3KO mice and Apoe-/- Mettl3flox/flox mice." (PMID 35001873, 2022). "miR-33a-5p inhibits ox-LDL-induced VSMC calcification via binding to METTL3 during atherosclerosis development." (PMID 36237831, 2022). "In the advanced stages of atherosclerosis, METTL3 expression was significantly upregulated between Stage 4 and Stage 1 (p < 0.001)." (PMID 36230944, 2022). "In the context of aneurysms, similar to how METTL14 promotes DGCR8-mediated processing of pri-miR-19a in atherosclerosis, METTL3-dependent m6A methylation promotes primary miR-34a maturation through DGCR8, leading to decreased SIRT1 expression and an aggravated aneurysm formation." (PMID 40005339, 2025). "To clarify whether H19 was involved in the process of METTL3 aggravating atherosclerosis, we first consulted the SRAMP database and learned that H19 had as many as 41 potential m6A modification sites." (PMID 39432244, 2024). "Figure S1METTL3 expression in the aorta of mice with atherosclerosis (AS).A.Relative mRNA expression levels of METTL3 in control, AS, AS+siNC, and AS+si‐METTL3 groups; B. Representative Western blot images and quantification of METTL3 protein levels, normalized to β‐actin, across the same groups." (PMID 39432244, 2024). "After discovering that METTL3 was highly expressed in both the animal and cell models of atherosclerosis, we hypothesized that the level of METTL3 expression might affect HAEC function." (PMID 39432244, 2024).
atherosclerosis (continued). "While METTL3 is primarily recognized for its involvement in RNA modification and processing, recent investigations have indicated its potential contribution to cardiovascular diseases, such as atherosclerosis." (PMID 38169612, 2024). "Therefore, METTL3 regulated the expression level of H19 by direct m6A modification in both the animal and cell models of atherosclerosis." (PMID 39432244, 2024). "Thus, METTL3 promoted atherosclerosis progression by upregulating H19 expression levels in vivo and in vitro." (PMID 39432244, 2024). "The RT‐qPCR and western blotting results showed that both mRNA and protein levels of METTL3 and METTL14 in the aortas of mice in the atherosclerosis group were notably increased compared with mRNA and protein levels of METTL3 and METTL14 in the Control group (p < .05)." (PMID 39432244, 2024). "Thus, the controversy surrounding the association between H19 and pyroptosis prompted us to focus on H19 in our investigation to elucidate the mechanism of atherosclerosis induction by METTL3." (PMID 39432244, 2024). "Finally, in vivo experiments further verified the influence of METTL3‐mediated m6A modification and H19 expression in atherosclerosis." (PMID 39432244, 2024). "In coronary segments, the upregulation of METTL3 confirmed its role in atherosclerosis." (PMID 36230944, 2022). "Notably, METTL3-mediated m6A RNA deposition has been suggested to have a key role in early atherosclerosis." (PMID 35991314, 2022). "The aim of this study was to provide a comprehensive survey of m6A methylation and expression features of mRNAs in the proliferation and migration of HCASMCs, and to elucidate the regulatory role of METTL3 to provide treatment directions and possibilities for atherosclerosis." (PMID 36230944, 2022). "Our findings suggest that targeting METTL3 in vascular proliferative diseases like atherosclerosis and restenosis could be a viable option." (PMID 36386358, 2022). "Overall, our findings highlight the importance of METTL3-mediated m6A in VSMCs phenotype switching and offer a novel perspective on targeting METTL3 as a therapeutic option for VSMCs phenotype switching modulated pathogenesis, including atherosclerosis and restenosis." (PMID 36386358, 2022). "The increased expressions of METTL3 and YTHDF2 in macrophages of atherosclerosis promoted the occurrence of inflammation." (PMID 40225569, 2025). "Our results showed that the expression levels of m6A, METTL3, and METTL14 were significantly increased in cell and animal models of atherosclerosis." (PMID 39432244, 2024). "First, we explored the expression of key writer proteins METTL3 and METTL14 in animal and cell models of atherosclerosis during m6A modification." (PMID 39432244, 2024). "The results showed that m6A, METTL3, and METTL14 expression levels in the atherosclerosis experimental models were much higher than those in the control models." (PMID 39432244, 2024). "As reported in a meta‐analysis, the expression levels of METTL3 and METTL14 were increased in vascular endothelial cell, macrophage, and smooth muscle cell models of atherosclerosis, consistent with our study findings." (PMID 39432244, 2024). "In contrast with the atherosclerosis+si‐METTL3+vector group, serum TC, TG, and LDL‐C levels in mice in the atherosclerosis+si‐METTL3+H19 group significantly increased (p < .05), while the HDL‐C level markedly decreased." (PMID 39432244, 2024). "HDGF knockdown alleviated inflammation, glycolysis, and lipid accumulation in M1 macrophages, while high METTL3 expression in macrophages increased HDGF levels through m6A modification, thereby aggravating atherosclerosis." (PMID 37671161, 2023). "We also observed the impact of METTL3 knockdown on the biological behavior of the atherosclerosis cell model, particularly focusing on HAEC pyroptosis, given the critical role of endothelial cell dysfunction in the pathogenesis of atherosclerosis." (PMID 39432244, 2024).
atherosclerosis (continued). "Overall, our study revealed that METTL3 alleviates endothelial atherogenic progression through m6A-dependent stabilization of EGFR mRNA, highlighting the important role of RNA transcriptomics in atherosclerosis regulation." (PMID 35001873, 2022). "Secondly, the molecular mechanisms and functional experiments in this study were less than perfect, and the specific mechanisms by which METTL3 may participate in the pathological process of HCASMCs and the development of atherosclerosis were not explored." (PMID 36230944, 2022). "However, whether METTL3 could impact the proliferation and migration of SMCs in atherosclerosis has not been fully elucidated." (PMID 36230944, 2022). "In addition, METTL3/METTL14 and m6A methylation have been reported to play roles in other diseases such as heart failure, viral infection, type 2 diabetes, cardiac remodeling, atherosclerosis, congenital heart disease, inflammation, obesity, insulin resistance, adipogenesis, and hypertension." (PMID 35211628, 2022).
oral squamous cell carcinoma (25 papers, 2021 to 2025). "Also, METTL3 was found to be consistently upregulated, and high METTL3 expression was associated with the prognosis of oral squamous cell carcinoma patients." (PMID 35813476, 2022). "Our results revealed a previously uncharacterized regulatory axis in NPC that is distinct from the METTL3-YTHDF1-c-MYC pathway reported in oral squamous cell carcinoma." (PMID 41167308, 2025). "Most of them are concentrated in oral squamous cell carcinoma; for example, METTL3 depletion profoundly reduced cell proliferation, cell migration, oncogenicity, and cisplatin resistance of arecoline-exposed OSCC cells." (PMID 38283119, 2024). "METTL3 downregulation inhibited the invasion, migration, and proliferation of oral squamous cell carcinoma (OSCC) cells by decreasing the m6A modification of protein arginine methyl transferase 5 (PRMT5) and programmed death-ligand 1 (PD-L1)." (PMID 36835633, 2023). "Accordingly, in oral squamous cell carcinoma, METTL3 can collect the m6A reader YTHDF1 to facilitate their target c-MYC transcript stability." (PMID 37259333, 2023). "METTL3/ METTL14 upregulation enhanced the resistance of oral squamous cell carcinoma (OSCC) to cisplatin by inhibiting the interleukin -17 (IL-17) signaling." (PMID 36835633, 2023). "One study showed that METTL3 increased the expression of PD-L1 and intensified the malignant phenotype in oral squamous cell carcinoma." (PMID 36212476, 2022). "In oral squamous cell carcinoma, METTL3 promotes tumorigenesis and metastasis through BMI1 m6A methylation." (PMID 35399719, 2022). "The METTL3 gene was also found to be upregulated in oral squamous cell carcinoma (OSCC) patients from TCGA database analysis and independent cancerous clinical samples." (PMID 34207099, 2021). "METTL3 facilitates oral squamous cell carcinoma tumorigenesis by strengthening the c‐Myc stability via YTHDF1‐mediated m6A modification." (PMID 34151473, 2021). "Till now, the functions of METTL3 in oral squamous cell carcinoma (OSCC) and its relative mechanism remain to be explored." (PMID 34476262, 2021). "Furthermore, METTL3 also triggered the malignant progression of Oral Squamous Cell Carcinoma by promoting m6A modification and stabilization of c-Myc." (PMID 38961325, 2024). "Up-regulation of METTL3 expression in oral squamous cell carcinoma (OSCC) promotes OSCC cell proliferation, self-renewal, migration, and invasive processes, mainly through BMI1 m6 A methylation at the post-transcriptional level to facilitate the translation of BMI1 in OSCC." (PMID 39289775, 2024). "METTL3 can modify fibroblast growth factor receptor (FGFR3, an anlotinib target) m6 A methylation in oral squamous cell carcinoma (OSCC), and the knockdown of METTL3 enhances anlotinib sensitivity of OSCC cells." (PMID 40483535, 2025). "This study determined METTL3 expression in normal oral mucosa (NOM), OED, and oral squamous cell carcinoma (OSCC) by immunohistochemistry." (PMID 35785826, 2023). "Also, in oral squamous cell carcinoma (OSCC), METTL3 was significantly upregulated in tissue samples and correlated with the poor prognosis of OSCC patients." (PMID 38966069, 2024). "Additionally, METTL3 could enhance the stability of c-MYC through YTHDF1-mediated m6A modification and promote tumorigenesis in oral squamous cell carcinoma." (PMID 36675186, 2023).